CAPRIN1 (cell cycle associated protein 1)
Diseases named in the same sentence as CAPRIN1 in open-access papers (continued):
Sharing a sentence is not in itself a finding about the gene and the disease.
prostate carcinoma (2 papers, 2019 to 2022). A carcinoma that arises from epithelial cells of the prostate gland. "Collectively, these data suggest that SPOP mutations result in elevated Caprin1 protein abundance that associated with prostate cancer progression." (PMID 31771591, 2019). "Next, we investigated the impact of prostate cancer-associated mutants of SPOP on Caprin1 localization." (PMID 31771591, 2019). "SPOP WT suppresses SG assembly, while the prostate cancer-associated mutants enhance SG assembly in a Caprin1-dependent manner." (PMID 31771591, 2019). "As PSA is a strong predictor of prostate cancer prognosis, it can be inferred that Caprin1 protein level might be associated with the aggressiveness of prostate cancer." (PMID 31771591, 2019). "Increased Caprin1 expression correlates with SPOP mutation status in prostate cancer specimens." (PMID 31771591, 2019). "Our study reveals that SPOP mutations augment Caprin1-mediated SG assembly and render prostate cancer cells resistance to docetaxel, suggesting that targeting the SG assembly pathway represents a viable strategy to restore docetaxel sensitivity in prostate cancer cells." (PMID 31771591, 2019). "We postulated that prostate cancer-associated mutants of SPOP may be defective in mediating Caprin1 destruction." (PMID 31771591, 2019). "To examine the effect of SPOP mutations on Caprin1 protein levels in prostate cancer specimens from patients, we analyzed Caprin1 protein levels by immunohistochemistry (IHC) methods in a cohort for which a total of 131 primary prostate tumor samples were available." (PMID 31771591, 2019). "Caprin1 plays minimal roles in prostate cancer proliferation and migration in vitro, but is important for cell survival under stress conditions and tumor growth in vivo." (PMID 31771591, 2019). "Caprin1 abundance is elevated in SPOP-mutant expressing prostate cancer cell lines and patient specimens." (PMID 31771591, 2019). "Depletion of SPOP by short hairpin RNA (shRNA)-mediated knockdown or CRISPR/Cas9-mediated knockout in multiple prostate cancer cell lines resulted in a marked increase in the steady-state levels of endogenous Caprin1)." (PMID 31771591, 2019). "WT SPOP suppresses SG assembly and promotes stress-induced cell death in prostate cancer cells by targeting Caprin1 for ubiquitin-dependent degradation, and this effect is abrogated by prostate cancer-associated SPOP mutations." (PMID 31771591, 2019). "Taken together, our data demonstrate that the SPOP–CUL3–RBX1 E3 ubiquitin ligase complex regulates Caprin1 protein stability through ubiquitin-dependent proteasomal degradation in prostate cancer cells." (PMID 31771591, 2019). "Caprin1 was ubiquitnously expressed in various prostate cancer cell lines." (PMID 31771591, 2019). "We explored whether Caprin1 is an authentic SPOP substrate, and whether its physiological function is dysregulated in SPOP-mutated prostate cancer." (PMID 31771591, 2019). "To determine the biological importance of SPOP regulation of Caprin1-mediated SG assembly in prostate cancer, we first investigated whether Caprin1 expression is important for maintaining the neoplastic phenotypes of prostate cancer cells." (PMID 31771591, 2019). "Docetaxel, the most commonly-used therapeutic drug in prostate cancer, induced much more SGs in SPOP knockdout cells but less SGs in Caprin1 knocout cells compated with that in control cells." (PMID 31771591, 2019). "Wild-type SPOP, but not the prostate cancer-associated SPOP mutants, suppresses SG assembly by promoting ubiquitination and degradation of Caprin1, a SG nucleating oncoprotein previously found overexpressed in various cancers." (PMID 31771591, 2019). "In addition to Caprin1, G3BP2 expression is an independent prognostic factor predicting poor outcome in prostate cancer." (PMID 31771591, 2019).
prostate carcinoma (continued). "However, knockout or overexpression of Caprin1 alone had no obvious effect on the DNA synthesis, cell cycle progression, cell growth and migration in prostate cancer cells." (PMID 31771591, 2019).
anaplastic large cell lymphoma (1 paper, 2023). Anaplastic large cell lymphoma (ALCL) is a rare and aggressive peripheral T-cell non-Hodgkin lymphoma, belonging to the group of CD30-positive lymphoproliferative disorders, which affects lymph nodes and extranodal sites. "Other FRK‐related fusion genes, including CAPRIN1::FRK, PABPC1::FRK, and MAPK9::FRK, have been identified in ALK‐negative anaplastic large cell lymphoma (ALCL)." (PMID 37601849, 2023).
diabetic nephropathy (1 paper, 2023). "The Caprin-1 gene has been found to be downregulated in B2R knockout (B2R−/−) mice, a mouse model of diabetic nephropathy." (PMID 36769128, 2023).
disc degeneration (1 paper, 2023). "The change in the number and intensity of CAPRIN1-immunopositive cells among the different grades of Pfirrmann MRI classifications may reflect a change in cell proliferative activity during the progression of disc degeneration." (PMID 36982840, 2023).
esophageal carcinoma (1 paper, 2023). A primary or metastatic malignant neoplasm involving the esophagus. "Cytoplasmic activation/proliferation-associated protein-1 (Caprin-1) is implicated in cancer cell proliferation and tumorigenesis; however, its role in the development of esophageal carcinoma (ESCA) has not been examined." (PMID 36855123, 2023).
laryngeal carcinoma (1 paper, 2022). Carcinoma that arises from the laryngeal epithelium. "In this study, we identified that CAPRIN1 was upregulated in the laryngeal cancer tissues and associated with poor prognosis in patients with laryngeal cancer." (PMID 35571493, 2022). "The underlying mechanism investigation revealed that CAPRIN1 promoted glycolysis and chemoresistance in laryngeal cancer cells was mediated by its interaction with ZIC5." (PMID 35571493, 2022). "The underlying mechanistic investigation revealed that CAPRIN1 promoted glycolysis and chemoresistance of laryngeal cancer cells by the regulation of Zic Family Member 5 (ZIC5)." (PMID 35571493, 2022). "An elevation of CAPRIN1 was identified to be associated with chemoresistance and poor prognosis in patients with laryngeal cancer." (PMID 35571493, 2022). "In this study, we further investigated whether the roles of CAPRIN1 in laryngeal cancer were associated with glycolysis." (PMID 35571493, 2022). "In addition, high expression of CAPRIN1 was associated with poor prognosis in patients with laryngeal cancer." (PMID 35571493, 2022). "Interestingly, high expression of CAPRIN1 was associated with patients with laryngeal cancer." (PMID 35571493, 2022). "The regulatory effects of CAPRIN1 on glycolysis and chemoresistance of laryngeal cancer cells were correlated to its interactions with the ZIC5 3′UTR region." (PMID 35571493, 2022). "We investigated the expressions of CAPRIN1 in laryngeal cancer and ANT tissues and found that the expressions of CAPRIN1 in laryngeal cancer tissue were significantly higher than those in the ANT tissue." (PMID 35571493, 2022). "Supportively, the percentage of the abundance of CAPRIN1 in laryngeal cancer tissue was also higher than that in the ANT tissue." (PMID 35571493, 2022). "In this study, we found that CAPRIN1 was highly expressed in laryngeal cancer tissues as compared to adjacent normal tissues." (PMID 35571493, 2022). "Taken together, these results suggested that CAPRIN1 promoted glycolysis and chemoresistance of laryngeal cancer cells by the regulation of ZIC5." (PMID 35571493, 2022). "The increase of CAPRIN1 promoted glycolysis and chemoresistance, whereas the knockdown of CAPRIN1 inhibited glycolysis and chemoresistance in laryngeal cancer cells." (PMID 35571493, 2022). "Taken together, these results suggested that CAPRIN1 promoted glycolysis and chemoresistance in laryngeal cancer cells by regulation of ZIC5." (PMID 35571493, 2022). "Consistently, the protein expressions of CAPRIN1 in cisplatin-resistant cell lines were higher than those in laryngeal cancer cell lines." (PMID 35571493, 2022). "To confirm the roles of CAPRIN1 in glycolysis and chemoresistance, we then knocked down CAPRIN1 in other two laryngeal cancer cell lines, TU-177 and TU-177/R cells." (PMID 35571493, 2022). "The results demonstrated that knockdown of CAPRIN1 suppressed cell viability of laryngeal cancer cell lines that were treated by cisplatin, indicating that CAPRIN1 knockdown suppressed cisplatin-resistance in laryngeal cancer cells." (PMID 35571493, 2022). "In this study, ZIC5 was identified as a target of CAPRIN1 in laryngeal cancer." (PMID 35571493, 2022). "In addition, we observed a significant elevation of the mRNA expression levels of CAPRIN1 in laryngeal cancer tissue." (PMID 35571493, 2022). "Furthermore, cell viability assays demonstrated that the cell viability and colony number of TU-177/R cells were significantly decreased in the treatment of cisplatin, indicating that CAPRIN1 knockdown suppressed cisplatin resistance in laryngeal cancer cells." (PMID 35571493, 2022). "Interestingly, upregulated CAPRIN1 promoted glycolysis and cisplatin resistance, whereas CAPRIN1 knockdown suppressed glycolysis and cisplatin resistance in laryngeal cancer cells." (PMID 35571493, 2022).
laryngeal carcinoma (continued). "In addition to investigating the expressions of CAPRIN1, we also evaluated the relationship between CAPRIN1 expression and overall survival rate in patients with laryngeal cancer." (PMID 35571493, 2022). "However, the roles of CAPRIN1 in laryngeal cancer are still unclear." (PMID 35571493, 2022). "In addition, cell viability assays showed that cisplatin-treated CAPRIN1 overexpressing Hep-2 cells exhibited higher cell viabilities and numbers of colonies as compared to those normal Hep-2 cells, indicating CAPRIN1 overexpressing promoted cisplatin resistance in laryngeal cancer cells." (PMID 35571493, 2022).
laryngeal squamous cell carcinoma (1 paper, 2022). A squamous cell carcinoma that arises from the larynx. "This study was designed to investigate the roles of CAPRIN1 in glycolysis and chemoresistance and its underlying mechanisms in laryngeal squamous cell carcinoma." (PMID 35571493, 2022). "Therefore, in this study, we aimed to investigate the roles of CAPRIN1 in laryngeal squamous cell carcinoma and its underlying mechanisms." (PMID 35571493, 2022). "CAPRIN1 promoted laryngeal squamous cell carcinoma glycolysis and chemoresistance by the regulation of ZIC5." (PMID 35571493, 2022). "Cytoplasmic activation/proliferation-associated protein-1 (CAPRIN1) plays an important role in carcinogenesis, whereas its role in laryngeal squamous cell carcinoma remains unclear." (PMID 35571493, 2022). "However, the roles of CAPRIN1 in laryngeal squamous cell carcinoma are still unknown." (PMID 35571493, 2022).
lung carcinoma (1 paper, 2022). "In lung cancer, SNHG9 played a role in cisplatin resistance by promoting the CAPRIN1 gene, and the knockdown of SNHG9 decreased cell proliferation and invasion." (PMID 35887228, 2022).
lymph node metastasis (1 paper, 2023). "Increased levels of Caprin-1 mRNA and protein expression were associated with lymph node metastasis and PET metabolic parameters in ESCA patients." (PMID 36855123, 2023). "Caprin-1 expression in ESCC patients was significantly associated with lymph node metastasis (P = 0.031), Ki-67 expression (P = 0.023), SUVmax (P = 0.002), and SUVmean (P = 0.005), but not with gender, age, tumor size, differential status, p stage, TLG or MTV." (PMID 36855123, 2023). "Lymph node metastasis (P = 0.022) and SUVmax (P = 0.048) were strongly correlated with Caprin-1 expression." (PMID 36855123, 2023). "A significant positive correlation was observed between high Caprin-1 protein levels and lymph node metastasis (P = 0.031), ki-67 (P = 0.023), and 18F- FDG PET/CT parameters (SUVmax (P = 0.002) and SUV mean (P = 0.005)) in 55 ESCA patients." (PMID 36855123, 2023).
metastatic cancer (1 paper, 2023). A carcinoma which has spread from the original site of growth to another anatomic site. "Notably, the membrane expression of CAPRIN-1 extended to the subset of highly tumorigenic cancer stem cells and epithelial–mesenchymal transition (EMT)–induced metastatic cancer cells." (PMID 37082579, 2023).
metastatic disease (1 paper, 2023). "While EMT induction resulted in a marked downregulation of well-known epithelial cancer markers such as E-Cadherin, rendering such epithelial surface markers rather inappropriate for targeting of metastatic disease, there was still high surface expression of CAPRIN-1." (PMID 37082579, 2023).
thyroid cancer (1 paper, 2024). "Circ_0004851 originates from the CAPRIN1 gene’s exons 12–14 and remains unexplored in thyroid cancer research." (PMID 38902782, 2024).
cancer (33 papers, 2013 to 2025). A tumor composed of atypical neoplastic, often pleomorphic cells that invade other tissues. "In conclusion, our preliminary findings showed that Caprin-1 was highly expressed in cancer tissues and significantly associated with prognosis in diverse cancer types." (PMID 36855123, 2023). "Caprin-1 was reported to be aberrantly expressed in various cancers and associated with poor prognosis." (PMID 36732659, 2023). "Cytoplasmic activation/proliferation-associated protein-1 (Caprin-1), is involved in neurodegenerative diseases and various cancers." (PMID 36855123, 2023). "Caprin-1 depleted carcinoma cells become more resistant to tylophorine, associated with decreased formation of the ribonucleoprotein complex targeted by tylophorine." (PMID 25669982, 2015). "Several studies have also demonstrated that the intracellular expression of CAPRIN-1 is positively correlated with cancer progression and poor prognosis, suggesting that CAPRIN-1 could be a diagnostic biomarker and a suitable cancer therapeutic target." (PMID 40557916, 2025). "Moreover, SPOP mutations enhance cancer cell survival and resistance to docetaxel, a synthetic analog of paclitaxel by upregulating Caprin1-dependent SGs." (PMID 31771591, 2019). "Thus, tylophorine compounds exert anti-cancer activity predominantly by targeting and sequestering the caprin-1 protein and c-Myc mRNA associated ribonucleoprotein complex." (PMID 25669982, 2015). "Therefore, emerging evidence in other cancers might help elucidate the mechanisms underlying the oncogenic roles of CAPRIN1 in NPC." (PMID 36515758, 2022). "Future research should expand the sample size and explore the role of the LINC02544/miR-497-5p/CAPRIN1 axis in other cancer types." (PMID 40819077, 2025). "SPOP specifically regulates Caprin1-dependent SG assembly in C4-2 cells, and PCa-associated SPOP mutations enhance cancer cell survival by elevating Caprin1 levels." (PMID 40521202, 2025). "It has been suggested that TRK-950, which shows high affinity for CAPRIN-1, a protein strongly expressed on the surface of cancer cells, is mainly distributed in the circulating blood and tumor tissue." (PMID 40557916, 2025). "In cancer cells, part of the total CAPRIN-1 is exposed on the cell membrane surface, a phenomenon that is not observed in noncancerous cells." (PMID 40557916, 2025). "To further verify the reliability of our conclusion, we validated the regulation of CAPRIN1 on cancer-specific m6A by knocking down CAPRIN1." (PMID 38970366, 2024). "Recent studies have revealed that Caprin-1 expression is functionally required for glutamine metabolism, which also involves cell proliferation and metastasis in various cancers." (PMID 36855123, 2023). "We then investigated the roles of Caprin-1 on cancer cell proliferation using EdU cell proliferation assay and colony formation." (PMID 38082307, 2023). "The specificity of cancer cell membrane binding anti-CAPRIN-1 antibodies we generated was confirmed by (i) competition assays using soluble recombinant CAPRIN-1 and (ii) abolished binding to CAPRIN-1–deficient cancer cells following CAPRIN-1 knockdown." (PMID 37082579, 2023). "A result of the SEREX screening using both serum of mammary gland tumor-bearing dog and canine testis tissue, we identified CAPRIN-1 as a novel candidate target for cancer treatment." (PMID 37082579, 2023). "On the basis of the rabbit mAb (mAb-1) that reliably identifies CAPRIN-1 on the surface of cancer cell membranes, the humanized anti-CAPRIN-1 antibody (TRK-950) was generated." (PMID 37082579, 2023). "As a result of the knockdown of CAPRIN-1 in cancer cells, dead cells increased, suggesting the possibility that CAPRIN-1 is indispensable for cancer cell survival." (PMID 37082579, 2023).